SNORA52 (small nucleolar RNA, H/ACA box 52)
Synonyms: ACA52
Gene: Small nucleolar RNA gene on chromosome 11 (811,681 to 811,814, forward strand). Ensembl gene ENSG00000199785.
Gene Ontology:
Biological process: RNA processing
Cellular component: nucleolus
Homologues: Orthologues: macaque SNORA52 (96% identical), chimpanzee SNORA52 (96% identical), pig SNORA52 (83% identical), dog SNORA52 (82% identical), guinea pig SNORA52 (79% identical), rat Snora52 (72% identical), mouse Snora52 (68% identical), mouse Gm54463 (43% identical).
Diseases named in the same sentence as SNORA52 in open-access papers:
SNORA52 is named in the same sentence as 2 diseases in open-access papers, as found by Europe PMC text mining. Sharing a sentence is not in itself a finding about the gene and the disease. The quoted sentences say what the papers report.
hepatocellular carcinoma (2 papers, 2022 to 2024). A malignant tumor that arises from hepatocytes. "SNORA52 is downregulated in hepatocellular carcinoma (HCC) and has been proved to inhibit its development." (PMID 39516455, 2024). "According to a recent study, low expression of snoRA52 is related to poor long-term survival in hepatocellular carcinoma." (PMID 36158687, 2022).
glaucoma (1 paper, 2023). Increased pressure in the eyeball due to obstruction of the outflow of aqueous humor. "Additionally, SNORD3A, SNORD16, SNORA52, and SNORA23 were differentially expressed in patients with glaucoma." (PMID 37805546, 2023).